MMP14 (matrix metallopeptidase 14)
Diseases named in the same sentence as MMP14 in open-access papers (continued):
Sharing a sentence is not in itself a finding about the gene and the disease.
glioma (continued). "While microglia in the healthy brain do not express MMP14, it is upregulated in glioma-associated microglia through TLR-2." (PMID 36768141, 2023). "This upregulation stabilizes lncRNA OIP5-AS1, which in turn, binds to miR-495-3p and decreases the association of miR-495-3p, hypoxia-inducible factor 1 alpha (HIF1A), and matrix metalloproteinase 14 (MMP14) mRNA, ultimately promoting the formation of vasculogenic mimicry in glioma." (PMID 37391814, 2023). "Additionally, the upregulation of MMP14 reduced the inhibitory effects of overexpressed miR‐374b‐5p in glioma cells." (PMID 34890108, 2022). "Similarly, the lncRNA PHAROH regulates Myc translation in hepatocellular carcinoma by sequestering TIAL1, and the lncRNA LOXL1-AS1 interacts with TIAR to modulate vasculogenic mimicry in glioma through the regulation of the miR-374b-5p/MMP14 axis." (PMID 35887183, 2022). "We also proved that MMP14 promotes malignant cell behaviours in gliomas." (PMID 34890108, 2022). "The low expression of miR-155 in IDH1-mutant glioma can upregulate the expression of FAM133A, which may further reduce the invasiveness and proliferation of IDH1-mutant glioma by targeting Matrix metalloproteinase-14 (MMP14)." (PMID 35677036, 2022). "Additionally, miR‐374b‐5p overexpression repressed malignant biological behaviours and VM in glioma by modifying MMP14." (PMID 34890108, 2022). "Our study shows that the TIAR/LOXL1‐AS1/miR‐374b‐5p/MMP14 axis has significant effects in regulating VM in glioma, which could help reveal novel targets for glioma therapy." (PMID 34890108, 2022). "Moreover, LOXL1‐AS1 knockdown upregulated miR‐374b‐5p, leading to the downregulation of MMP14, eventually suppressing malignant cell behaviour and VM in glioma cells." (PMID 34890108, 2022). "The mRNA expression and RNASeq of matrix metalloproteinase 2 (MMP2) and matrix metalloproteinase 14 (MMP14) is presented for differing grades of glioma using the Gliovis data portal for visualization and analysis of brain tumor expression datasets to analyze data from the TCGA and the CCGA." (PMID 33919029, 2021). "In another study, miR-133b was shown to suppress glioblastoma invasion and cell migration via downregulation of metalloproteinase 14 (MMP14) in U87 and U251 glioma cells, while miR-133b was also shown to impede proliferation and invasion of glioma due to Sirt1 downregulation." (PMID 34660740, 2021). "Moreover, OAT-1746 treatment affects the expression of genes involved in leukocyte chemotaxis (Ccl2, Ccl7, Ccl17) and supporting glioma migration and invasion (Cme1, S100a4 and Mmp14)." (PMID 34504786, 2021). "Studies have shown that MMP-14 can be used as a prognostic marker for patients with glioma." (PMID 34712139, 2021). "While microglia in the healthy brain do not express MMP14, it is upregulated in glioma associated GAMs." (PMID 32331440, 2020). "In glioma cells, MMP14 activity in the lamellipodia mediates glioma migration." (PMID 32872536, 2020). "A competing idea states that microglial MMP14 enables glioma cell infiltration." (PMID 32872536, 2020). "Moreover, the protein levels of CD44, β-catenin, N-cadherin, Vimentin, and MMP14 were also decreased in miR-124-3p overexpressing glioma cells and increased in miR-124-3p deprived cells." (PMID 32127518, 2020). "We thus hypothesized that IL-6 was also involved in regulating MMP14 expression through the activation of MMP2 or MMP9 in glioma." (PMID 27613828, 2016). "Furthermore, increased MMP14 expression correlated with IL-6 expression in primary human glioma specimens." (PMID 27613828, 2016). "miR-10b induces glioma cell invasion by modulating MMP-14 and uPAR expression via HOXD10." (PMID 26311318, 2015). "High expression of MMP14 was reported in lung cancer and glioma." (PMID 26650241, 2015). "Besides, MMP14 has also been shown to be a direct target of miR-10b in glioma, miR-9 in neuroblastoma and miR-133a in esophageal cancer." (PMID 25268950, 2014).
glioma (continued). "In our present study, we suggest a similar regulatory mechanism of miR-23a promoting glioma cell invasion via downregulating HOXD10, which further upregulates the expression of MMP-14, a key factor implicated in extracellular matrix breakdown in physiological or pathological processes." (PMID 24305689, 2013). "We show that MMP14 correlates with glioma aggressiveness and patient survival." (PMID 24156018, 2013). "Moreover, the MMP-14 inhibitor, Marimastat, induces glioma cell cycle arrest and slows tumor progression." (PMID 24156018, 2013). "Inhibition of MMP14 with shRNA silencing led to cell cycle arrest of glioma cells in G2 phase." (PMID 24156018, 2013). "To assess whether TMZ and XRT will benefit from MMP14 silencing, we divided U251 glioma-bearing mice into four different treatment groups: shScramble, shMMP14, shScramble+TMZ+XRT, and shMMP14+TMZ+XRT." (PMID 24156018, 2013). "To investigate whether MMP14 regulates cell division, we knocked down U87 and U251 glioma cells using shRNA technology." (PMID 24156018, 2013). "In the present study, we explored the role of MMP14 in the pathogenesis of glioma." (PMID 24156018, 2013). "Interestingly, as one of upstream regulator of IGFBP3, HoxD10 inhibits the migration and invasion of glioma and gastric cancer cells partly by modulating the expression of MMP14 and uPAR, which are both tumor invasion promoting factors." (PMID 24386080, 2013). "To identify profile of glioma-based miRNAs which regulate expression of MMP14 and are altered by TMZ/XRT treatment, we applied the miFinder SAbioscience platform to the total miRNAs isolated from U87 cells treated with TMZ/ XRT (100 μmol/L+2 Gy/daily) or DMSO for 48 h." (PMID 24156018, 2013). "Finally, silencing of MMP14 in U251 model significantly prolonged survival of mice treated with TMZ+XRT compared to the U251 shScramble (P < 0.009) which results in low glioma proliferation." (PMID 24156018, 2013). "Additionally, MMPs, including MMP-2 and MMP-14, facilitate the recruitment and migration of regulatory T-cells (Tregs) and myeloid-derived suppressor cells (MDSCs) into glioma tissue by remodeling extracellular matrix components and modulating chemokine gradients." (PMID 40265458, 2025). "Likewise, MMP14 is highly expressed in gliomas where it acts as a mediator of migration." (PMID 34890108, 2022). "Additionally, MMP14 acts as an oncogene in gliomas, while miR‐374b‐5p could mediate MMP14 expression by binding to their 3′UTRs, thus attenuating the malignant cell behaviours and VM in glioma." (PMID 34890108, 2022). "Thus, MMP-14 is extremely important in predicting the prognosis of patients with glioma." (PMID 34712139, 2021). "However, recent clinical trials have shown that the drug has good efficacy in BRAF V600E mutant malignant astrocytomas and low-grade gliomas; patients with high expression of MMP14 may predict the better curative effect of vemurafenib treatment." (PMID 34712139, 2021). "Finally, knockdown of MMP14 resulted in decreased glioma invasion and migration." (PMID 27613828, 2016). "Therefore, using flow cytometry, we investigated whether expression of cytomembrane MMP14 in glioma cells was also increased upon exposure to ACM." (PMID 27613828, 2016). "Therefore, this IL-6 and MMP14 axis between astrocytes and glioma cells may become a potential target for treatment of glioma patients." (PMID 27613828, 2016). "As expected, the conditioned medium from either GL261 or ALTS1C1 glioma cells significantly activated BV2 cells with a notable increase in pro-inflammatory cytokines, including IL-6, CCL-2, CXCL-10, MMP-14, TNFα, IL-1β, and iNOS." (PMID 41367876, 2025). "Recent advances have shifted the focus toward isoform-selective inhibitors targeting specific MMPs that are critical to glioma progression, notably MMP-9 and MMP-14." (PMID 40265458, 2025).
glioma (continued). "In glioma, inhibiting the TGF-β signaling pathway reduces the expression of MMP-14 and MT1-MMP, leading to a significant decrement in the formation of VM." (PMID 35747793, 2022). "TLR2 promotes TAM production of MMP14, which is essential for MMP2 release and glioma invasion, and the microglial expression of the metalloprotease MT1-MMP, which cleaves the pro-MMP2 into its active form, resulting in tumor invasion." (PMID 33766119, 2021). "TLR2 upregulates membrane type 1 matrix metalloprotease (MT1-MMP) and metallopeptidase 14 (MMP14) in MG to activate glioma-sourced MMP2 when responding to TLR2 endogenous ligands and thereby facilitate glioma invasion." (PMID 34671362, 2021). "The complex of MMP14, TIMP2, MMP2 and avß3 integrin leads to localized MMP2 activation and increases glioma cell migration in vitro." (PMID 32872536, 2020). "ANXA2P2 was positively correlated with genes that are related to glioma proliferation, invasion and angiogenesis, such as ANXA2, CD44, IL6, MMP14, MMP9, and VEGFA." (PMID 31681595, 2019). "Glioma cells secrete an array of proteases to be involved in glioma cell invasion, including MMP2 and MMP9, and the membrane-bound MMP, MT1-MMP (also known as MMP-14)." (PMID 29207533, 2017). "Data obtained from our study indicated that conditioned medium from M2 cells (M2-CM) increased the tubule formation number in glioma cells, as well as VM marker expression, including LAMC2, MMP-9 and MMP-14." (PMID 27903982, 2017). "Both increased IL-6 and MMP14 expression correlated with advanced WHO grade and poor overall survival in glioma patients." (PMID 27613828, 2016). "It has been recently reported that MMP14 is upregulated in response to TMZ and XRT exposure 21 and silencing of MMP, including MMP14, decreases glioma tumor formation in vivo 28–29." (PMID 24156018, 2013). "Previously, it has been shown that treatment of glioma cells with temozolomide (TMZ) and radiation (XRT) induces the expression of metalloproteinase 14 (MMP14)." (PMID 24156018, 2013). "Moreover, we found that R-2HG regulates the glioma microenvironment by decreasing IL-6, CCL2, CXCL10, and MMP-14 in microglia." (PMID 41367876, 2025). "This explains the fact that these MMPs have not received the same consideration as MMP14 in glioma research." (PMID 32872536, 2020). "Expression of the miR-23a may also indirectly target the repressor of the matrix metallopeptidase 14 (MMP14), homeobox D10 (HOXD10), and result in glioma cell migration." (PMID 30577536, 2018). "Moreover, the combination of MMP14 silencing with TMZ and XRT significantly improved the survival of glioma-bearing mice compared to a single modality treatment group." (PMID 24156018, 2013). "MMP-14 could also trigger COX-2 expression, as shown in a study using U87 glioma cells." (PMID 34685532, 2021). "MMP14 expression is known for its angiogenesis-promoting effect, therefore silencing of this protein is shown to reduce pro-angiogenic IL-8 and VEGF levels in infected glioma cells in vitro, as well as angiogenesis and glioma proliferation in human glioma xenografts." (PMID 33167307, 2020). "This work, however, was performed with MMP14-negative glioma cell lines, which showed cell death upon forced expression of MMP14 and therefore may apply to this rather rare situation only." (PMID 32872536, 2020). "Glioma-derived versican converts microglia into a pro-tumorigenic phenotype characterized by the upregulation of MMP9 and MMP14 (as observed here in response to LPA); in particular, MMP14 promotes activation of GBM-derived MMP2 that favors the invasive potential of malign glioblastoma cells." (PMID 29258556, 2017). "The results that cleavage of cytomembrane CD44 was not coordinately increased along with MMP14 indicated that MMP14 might enhance glioma migration and invasion not through cleavage of CD44 but rather through activation of MMP family members." (PMID 27613828, 2016).
glioma (continued). "Importantly, si-MMP14 did not significantly affect viability of glioma cells relative to the negative control sequences (NC) group." (PMID 27613828, 2016). "The research team found that there was an upregulation in IL-10, Osteopontin, MMP14, VEGF, TGF β, and CCL18 in samples containing both human stem cell derived microglial cells with human glioma cells, as opposed to samples containing human glioma cells alone." (PMID 36700223, 2022). "In glioma, whether miR-495-3p regulates the expression of HIF1A and MMP14 or the formation of VM has not been reported." (PMID 34345216, 2021).
melanoma (129 papers, 1999 to 2026). A malignant, usually aggressive tumor composed of atypical, neoplastic melanocytes. "The presence of MMP-14 has been associated with adverse outcomes in patients with various types of cancer, including melanoma." (PMID 39769318, 2024). "Loss of MMP14 in fibroblasts was shown to affect melanoma growth by altering the composition of the peritumoral extracellular matrix." (PMID 36052235, 2022). "Our in vivo data showed that deletion of MMP14 in fibroblasts is associated with increased collagen type I, skin stiffness, and melanoma growth inhibition levels." (PMID 33924099, 2021). "In vitro, we detected growth inhibition by culturing murine melanoma cells on matrices produced by MMP14-deficient fibroblasts, which macroscopically displayed enhanced matrix deposition." (PMID 34830157, 2021). "Altogether, our data demonstrate that loss of MMP14 activity in fibroblasts leads to enhanced tissue density and tension, thus inhibiting melanoma growth by attenuating angiogenesis and tumor cell proliferation." (PMID 33924099, 2021). "It was demonstrated also that BRAF and NRAS mutations positively regulate MMP-14 gene expression enhancing tumor growth and melanoma invasiveness in vivo." (PMID 32392801, 2020). "MALAT1 can promote the growth and metastasis of melanoma cells though sponging miR-22, functionally releasing MMP14 and Snail mRNA transcripts targeted by miR-22, causing MMP2 activation and E-cadherin down-regulation, and inducing ECM remodelling and EMT." (PMID 27564100, 2016). "Our data now suggest that specific inhibition of MMP14 might represent a more specific approach, as loss of this protease in fibroblasts resulted in reduced growth of grafted melanomas." (PMID 33924099, 2021). "Lumican, a specific member of the small leucine‐rich proteoglycan family, was shown to significantly decrease MMP‐14 activity in mice B16F1 melanoma cells." (PMID 41546170, 2026). "MMP‐14 is particularly relevant in melanoma progression as it activates other MMPs, such as MMP‐2 and promotes tumour cell migration by cleaving ECM components." (PMID 41546170, 2026). "A deeper look into SKCM datasets via TCGA validation revealed that MMP7, MMP11, and MMP14 also exhibited high expression in primary melanoma tumors." (PMID 40604111, 2025). "qRT-PCR in A375 melanoma cells showed significant overexpression of MMP7, MMP11, and MMP14 compared to normal skin cells, further supporting their relevance in melanoma." (PMID 40604111, 2025). "Immunohistochemistry from the Human Protein Atlas confirmed moderate to strong protein expression of MMP7, MMP11, and MMP14 in melanoma tissues, consistent with transcriptomic findings." (PMID 40604111, 2025). "Research conducted to date shows that lymphatic endothelial cells interact with MMP-14 on the membranes of melanoma cells, facilitating cell–cell interactions in metastatic melanoma cell lines." (PMID 39769318, 2024). "MALAT1 also triggered malignant melanoma growth and metastasis by sponging miR-22, consequently upregulating the miR-22 targets MMP14 and Snail." (PMID 38561330, 2024). "Prominent MMPs, including MMP-1, MMP-2, MMP-3, MMP-9, MMP-13, and MMP-14, have been shown to significantly contribute to the development of melanoma." (PMID 39769318, 2024). "Among them, monoclonal antibodies against MMP-14 have proven effective in preclinical studies of melanoma." (PMID 39769318, 2024). "More recently, MMP14 has been found to bind with and activate Notch1 on the melanoma cell membrane, hence increasing cell proliferation." (PMID 39769318, 2024). "Both the full-length 60 kDa and the proteolytically processed 43 kDa forms of MMP14 were detected in the exosomes of fibrosarcoma and melanoma cells." (PMID 35223528, 2022). "Among theothers, increased activation of ERK1/2 and MMP2, as well as upregulation of MMP14,have been reported in melanoma cells." (PMID 36046354, 2022).